GLI2 (GLI family zinc finger 2)
Diseases named in the same sentence as GLI2 in open-access papers (continued):
Sharing a sentence is not in itself a finding about the gene and the disease.
melanoma (continued). "It was previously reported that CREB-binding protein (CBP) is a transcriptional coactivator of GLI, and the MITF and GLI2 genes were found to be inversely expressed in various melanoma cell lines." (PMID 27941997, 2016). "We examined parallel sections of 35 randomly selected human tumors (lung carcinomas, ovary and tubal carcinomas and melanomas) and examined the GLI2 and survivin staining." (PMID 26775700, 2016). "SOX2is regulated by HH signaling where transcriptionfactorsGLI1 and GLI2 directly bind to the proximal promoter region of SOX2 in primary melanoma cells.Also, human SOX14 expression is GLI1 dependent in U87MG cells and SHH dependent in U87MG and HepG2 cells." (PMID 26588701, 2015). "A recent global genomic screening of 100 melanomas revealed few missense mutations in the core genes of the HH pathway (PTCH1, SMO, SUFU, GLI1, GLI2 and GLI3) (Ref." (PMID 25660620, 2015). "Further, GLI1 and/or GLI2 are oncogenes, and are constitutively activated in many types of human cancers including epithelial cancers of the GI tract, brain tumors, melanoma, pediatric solid tumors, liver, lung, breast, pancreatic and prostate cancers." (PMID 24962990, 2014). "Our findings in the WM278 cell line suggest that, in melanoma harboring amplification of GLI2, hedgehog target genes are constitutively transcribed and upstream inhibition of hedgehog signaling via SMO inhibitors is ineffective." (PMID 24287465, 2013). "GLI2 knockdown in melanoma cells dramatically reduces their capacity to form bone metastases, and its basal expression in melanoma cells depends on autocrine TGF-β signaling." (PMID 23984088, 2013). "Two studies also described high levels of GLI1 and GLI2 transcription factor mRNA in human metastatic melanoma tissue as compared to primary melanoma tissue." (PMID 24287465, 2013). "Our results indicate, that in those melanoma cells harboring GLI2 amplification, direct targeting of GLI2 is the best antitumor strategy." (PMID 24287465, 2013). "The mRNA coding for GLI2, one of the most important downstream effectors of Hh signaling, was markedly upregulated (7.59-fold increase) in melanoma cells, whereas two key Hh repressors, PTCH1 and SUFU, were significantly reduced (0.341 and 0.458-fold decrease, respectively) compared to controls." (PMID 41596411, 2026). "Furthermore, the SOX-BRD4 transcriptional complex induces the expression of GLI1 and GLI2 in human melanoma cells." (PMID 39962447, 2025). "Additionally, MMP9 is a crucial regulator implicated in ESCC outcome and prognosis, and its expression can be regulated by GLI2 in melanoma cells." (PMID 38924029, 2024). "Additionally, the investigators observed that targeting the Hh transcription factors GLI1 and GLI2 restored the sensitivity of human melanoma cells resistant to vemurafenib and even inhibited acquired chemotherapy resistance in melanoma patients." (PMID 39611156, 2024). "Notably, we observed strong significant correlations between SHH and Gli1 (p < 0.0001) and between SHH and Gli2 (p < 0.0001) in the immunohistochemical-staining melanoma samples." (PMID 37240209, 2023). "Similarly, the induction of vemurafenib resistance in melanoma cell lines was associated with frequent elevated expression of GLI1, while expression of GLI2 was elevated but to a lesser extent." (PMID 34572373, 2021). "Indeed, GLI2 was found to play a major role in suppressing MITF expression in human melanoma specimens, and the expression of GLI1/2 was correlated with EGFR/AXL signatures." (PMID 34572373, 2021). "In addition, oncogenic markers typical of basal cell carcinoma (Gli-1, Gli-2, Ptch-1, n = 2 cases) and melanoma (c-kit, MAGE, CDK4, n = 1) were markedly upregulated in skin lesions." (PMID 33509032, 2021). "Besides SOX2, the GLI transcription factors GLI1 and GLI2 have been suggested to be involved in melanoma progression and metastasis and to be responsible for maintenance of melanoma-initiating cells." (PMID 33203881, 2020).
melanoma (continued). "The TGF-β/Smad3 signaling pathway is also able to enhance Gli2 expression in melanoma." (PMID 33228057, 2020). "We established a role for both TGF-β signaling and GLI2 in driving melanoma invasion and metastasis, that could be targeted with TGF-β receptor inhibitors, the latter inhibiting GLI2 expression in tumor cells, or by knocking down GLI2 expression." (PMID 32879407, 2020). "While silencing GLI1 and GLI2 has recently been demonstrated to induce senescence to restore chemosensitivity in melanoma cells, Hh signaling has not yet been linked to senescence in GBM." (PMID 29930746, 2018). "In addition, we also found that serum starvation- and Cyto D-induced ciliogenesis was suppressed in GLI2 knockdown B16F1 mouse melanoma cells." (PMID 27941997, 2016). "CD271 knockdown was found to eliminate the capacity of melanoma cells to form heterogeneous tumors most likely through the downregulation of mediators for melanoma invasion and metastasis (GLI-2, SOX2 and ERBB3), angiogenesis (IGFBP-2), proliferation (FST and MITF) or chemoresistance (RHOJ)." (PMID 25351876, 2015). "Interestingly, while the melanoma cell lines used showed Smo and Ptch gene expression, Gli2 was found to be a transcriptional target of TGFβ signaling." (PMID 26343726, 2015). "Moreover, Gli2 cooperates with ZEB1 to transcriptionally repress of E-cadherin in melanoma, and TGF-β strongly enhances this complex formation." (PMID 25538895, 2014). "Moreover, GLI2 expression is associated with EMT, a critical event for the switch from an early radial growth phase to vertical growth phase of primary melanomas." (PMID 23984088, 2013). "GLI2 has been identified as direct TGF-β target, independent from the Hedgehog signaling, in cutaneous melanoma and has been associated with the most aggressive tumors in patients with melanoma." (PMID 23984088, 2013). "Additionally, it was postulated that GLI2 can mediate some TGF-β effects on melanoma bone metastasis." (PMID 23984088, 2013). "Notably, the MITF and GLI2 genes are inversely expressed in various melanoma cell lines." (PMID 27941997, 2016). "In melanoma cells, ERK5 silencing reduces GLI1 and GLI2 mRNA and protein levels and inhibits GLI transcriptional activity." (PMID 39998753, 2025). "In the present study, we examined the effects of the Gli1 and Gli2 dual inhibitor, GANT61, in a melanoma bone destruction mouse model and investigated its tumor suppressive mechanism." (PMID 37240209, 2023). "ChIP sequencing was used to identify GLI1, GLI2, and GLI3 binding regions in human melanoma cell lines and to further confirm RNA-seq results." (PMID 36139698, 2022). "In order to confirm HH-GLI pathway activation in melanoma cell lines, we analyzed relative gene and protein expression levels of the pathway components (GLI1, GLI2, GLI3, and PTCH1) on a panel of 14 human melanoma cell lines with different genetic backgrounds." (PMID 36139698, 2022). "We applied RNA sequencing and combined it with ChIP sequencing to identify direct but also unique and overlapping targets of GLI1, GLI2, and GLI3 in three melanoma cell lines." (PMID 36139698, 2022). "To gain further insight into the neoplastic potential of skin nevi, we evaluated the expression of oncogenic markers characteristic of BCC (Ptch-1, Gli-1, and Gli-2), SCC (K8, K17, and p63), and melanoma (c-kit, MAGE, and CDK4)." (PMID 33509032, 2021). "Examination of melanoma patient specimens failing vemurafenib revealed that all were positive for GLI1 expression, while 40% were positive for GLI2 expression." (PMID 34572373, 2021). "TGF-β is critical in the regulation of Gli2, which in turns has antagonistic effect on MITF expression, eventually leading to melanoma invasion and metastasis." (PMID 25538895, 2014). "SMO inhibition using siRNA and the small molecule inhibitor, NVP-LDE-225, suppressed melanoma growth in vitro, particularly in those cell lines with moderate SMO and GLI2 expression." (PMID 24287465, 2013).
melanoma (continued). "Studies revealed that over 40% of the melanoma cell lines examined harbored significantly elevated levels of the hedgehog pathway mediators SMO, GLI2, and PTCH1 compared to melanocytes (p < 0.05)." (PMID 24287465, 2013). "Although the role of HMGA2 in melanoma invasiveness is unknown, TGF-β/GLI2 and MITF inversely regulate invasion and pigmentation in melanoma cells, which is consistent with the present results." (PMID 24733089, 2014). "However, the direct effects of GANT61 on SHH, Gli1, and Gli2 expressions in melanoma cells were not evident, showing no significant change unlike the results of the in vivo analysis." (PMID 37240209, 2023). "The analysis of a bulk RNA-seq data set with a mixed cohort of melanoma and non-melanoma skin cancer patients revealed a significant positive correlation of IDO1 with GLI2 (R = 0.39, p < 0.01), supporting an in vivo involvement of the HH/GLI pathway in the induction of IDO1." (PMID 39962447, 2025).
osteosarcoma (32 papers, 2010 to 2025). A usually aggressive malignant bone-forming mesenchymal neoplasm, predominantly affecting adolescents and young adults. "Hedgehog pathway activation has been observed in osteosarcoma, and worse clinical outcomes are associated with overexpression of pathway components such as GLI2." (PMID 37176108, 2023). "In osteosarcoma studies, silencing of gli2 is found to cause upregulation of p21, inhibition of cyclin D1, SKP2, and phosphorylated Rb, thus inducing G1 phase arrest and ultimately preventing the growth of osteosarcoma." (PMID 37868974, 2023). "Studies conducted later revealed that ribosomal protein S3 was responsible for regulating osteosarcoma cell invasion caused by GLI2." (PMID 37176108, 2023). "A splice variant of p63, ΔNp63α, targets GLI2′s promoter to increase expression and is an important event in osteosarcoma progression during rare breast cancer forms." (PMID 33494284, 2021). "In addition, GLI2 amplifications have been associated with osteosarcoma development and metastasis, making it a potential target for therapy in these tumors." (PMID 40141463, 2025). "In the case of sarcomas, it has been shown that GLI1 and GLI2 can be overexpressed in various types of sarcomas, both in bone (osteosarcomas) and soft tissue (rhabdomyosarcomas)." (PMID 38275873, 2024). "This has been confirmed by knockdown of Gli2, which promoted the arrest of osteosarcoma cells in the G1 phase of cell cycle and inhibited osteosarcoma growth, demonstrated in murine xenograft models." (PMID 37815662, 2023). "Data report that Gli2 significantly promotes the proliferation, migration, and invasion of mesenchymal stem cells and osteosarcoma cells." (PMID 37815662, 2023). "The significance of GLI2 in human osteosarcoma has been extensively investigated in studies from the Setoguchi lab." (PMID 37176108, 2023). "Gene expression analyses by real-time PCR revealed overexpression of Shh, Ihh, Ptch1, Smo, and Gli2 in osteosarcoma cell lines." (PMID 37815662, 2023). "Another group confirmed higher expression of Gli1 and Gli2 in canine osteosarcoma cell lines compared to normal canine osteoblasts." (PMID 37815662, 2023). "GLI2 knockdown studies supporting its role in migration and invasion in osteosarcoma, prostate cancer, and hepatocarcinoma cell lines underscores the metastatic potential of GLI." (PMID 33494284, 2021). "Ligands SHH, DHH and IHH, Receptors Ptch1 and SMO, and transcription factors Gli1 and Gli2 are significantly overexpressed in human osteosarcoma cell lines, both at the mRNA and protein level." (PMID 32110934, 2020). "Gli1 and Gli2 showed expression predominantly in the nuclear compartment of osteosarcoma tumor cells." (PMID 32656074, 2020). "Gli2 is overexpressed in several osteosarcoma cells, and its overexpression is related to poor clinical results in osteosarcoma patients." (PMID 29899399, 2018). "On the other hand, knockdown of BCAR4 in-vitro using cell lines MG63 and U2-OS inhibits osteosarcoma cell proliferation and migration by inhibiting the transcription of GLI family zinc finger 2 (GLI2)-dependent target genes." (PMID 29657304, 2018). "The functional interactions between DeltaNp63alpha and GLI2 promote the tumourigenesis of osteosarcoma cells." (PMID 29899399, 2018). "GLI2 has been identified as a target for the treatment of osteosarcoma and the HH pathway has been reported to be important for osteosarcoma progression and metastasis." (PMID 30201866, 2018). "Elucidation of the function of DeltaNp63 in osteosarcoma shows that DeltaNp63alpha directly regulates the transcription factor Gli2." (PMID 29899399, 2018). "Further, we show that in osteosarcoma cells ΔNp63α directly regulated the transcription factor GLI2, which is a component of the hedgehog signaling pathway, and that functional interactions between ΔNp63α and GLI2 confer oncogenic properties upon OS cells." (PMID 25085524, 2014).
osteosarcoma (continued). "In summary, ΔNp63α regulates the expression of GLI2 and is involved in the metastasis of osteosarcoma." (PMID 25085524, 2014). "Here, we report that GLI2 is the novel target gene of ΔNp63α and that ΔNp63α-GLI2 crosstalk in osteosarcoma cells is a necessary event in osteosarcoma progression." (PMID 25085524, 2014). "Inhibition of the Hedgehog pathway by knockdown of SMO or GLI2 prevents osteosarcoma growth in vitro and in vivo." (PMID 23861973, 2013). "Real-time PCR showed that ATO decreased the expression of Hedgehog target genes, including PTCH1, GLI1, and GLI2, in human osteosarcoma cell lines." (PMID 23861973, 2013). "Real-time PCR revealed that ATO prevented the transcription of GLI target genes, including PTCH1, GLI1, and GLI2, in human osteosarcoma cell lines." (PMID 23861973, 2013). "In particular, we showed that knockdown of GLI2 prevented osteosarcoma cell growth in vitro and in vivo." (PMID 23861973, 2013). "Overexpression of Gli2 in human MSCs increases cell proliferation and progression through cell cycle regulation, and inhibition of Gli2 disrupted the growth of osteosarcoma cells." (PMID 22852096, 2012). "Cyclopamine at 20 μM reduced mRNA levels of PTCH1 and GLI2 in osteosarcoma cells by more than 60%, consistent with the expected down-regulation of Hh-GLI signaling." (PMID 20067614, 2010). "In the present study, we found that Shh, Dhh, PTCH1, SMO, GLI1 and GLI2 transcripts were over-expressed in osteosarcoma cell line." (PMID 20067614, 2010). "The link between Hedgehog and Wnt seems to be even more complicated as the existing evidence also indicates that GLI2 can promote nuclear localization of beta-catenin, thereby increasing Wnt signal transduction and driving cell proliferation of osteosarcoma cells." (PMID 38474826, 2024). "In addition, BCAR4 promotes the progression of osteosarcoma by activating the GLI2 signaling pathway." (PMID 39015175, 2024). "Moreover, recent findings indicate that ATO inhibits the transcriptional activity of Gli2 and inhibits osteosarcoma cell invasion." (PMID 37815662, 2023). "Additional evidence revealed that miR-141-3p could inhibit the expression of GLI2, downregulating parathyroid hormone-related protein 1 and promoting apoptosis in osteosarcoma cells." (PMID 35402517, 2022). "Importantly, overexpression of potent activated Gli2 in immortalized human mesenchymal stem cells stimulated their proliferation, reinforcing a role for Gli2 in osteosarcoma genesis as osteosarcoma cells are of mesenchymal origin." (PMID 32110934, 2020). "miR‐141‐3p suppresses cell PLF and enhances APS by targeting GLI2 in osteosarcoma." (PMID 32725768, 2020). "A high Gli2 expression could be shown in osteosarcoma cell lines, and a correlation of Gli2 expression with the prognosis of osteosarcoma patients was reported." (PMID 32656074, 2020). "Our data contribute to a better understanding of the role of the transcription factors, ΔNp63α and GLI2 in OS and suggest that the ΔNp63α-GLI2 axis may serve as a target for therapy of osteosarcoma." (PMID 25085524, 2014). "GLI2 was up-regulated 2.5-to 58.4-fold in 9 of 9 human biopsy specimens of osteosarcoma." (PMID 20067614, 2010). "Thus, RPS3 regulates Hh/Gli2 signalling in the invasion and metastasis of osteosarcoma." (PMID 29899399, 2018). "Importantly, interference of Gli2 inhibits osteosarcoma cell growth." (PMID 29899399, 2018). "Consequently, BCAR4 could serve as a therapeutic target in the treatment of osteosarcoma, as this would inactivate the GLI2 pathway and GLI2-dependent target genes." (PMID 29657304, 2018). "Also, rpS3 regulates GLI2-mediated cancer invasion and metastasis in osteosarcoma." (PMID 27384988, 2016). "In addition, SMO, PTCH1, and GLI2 were over-expressed in osteosarcoma biopsy specimens'." (PMID 20067614, 2010). "Decreased expressions of Gli1, Gli2, Ptch1, and PAX6 were observed after treatment of canine osteosarcoma cells using GANT61." (PMID 37815662, 2023).
osteosarcoma (continued). "Of most importance was the finding that markers of active Hhï¿1⁄2GLI signaling, GLI2 and PTCH1 were consistently up-regulated in the examined osteosarcoma cells, demonstrating the aberrant Hh-GLI pathway activation." (PMID 20067614, 2010). "To extend these findings, we performed immunocytochemistry for SMO and GLI2, and found that only osteosarcoma cells expressed detectable levels of SMO and GLI2." (PMID 20067614, 2010). "BCAR4 promotes proliferation and migration of osteosarcoma cells by regulating the nonclassical Hedgehog/GLI2 signaling pathway." (PMID 34048366, 2021). "Although GLI1 and GLI2 function as transcriptional activators of the Hh pathway, they have nonredundant roles in osteosarcoma." (PMID 25085524, 2014).